IGKV2D-28 (immunoglobulin kappa variable 2D-28)
Description:
V region of the variable domain of immunoglobulin light chains that participates in the antigen recognition. Immunoglobulins, also known as antibodies, are membrane-bound or secreted glycoproteins produced by B lymphocytes. In the recognition phase of humoral immunity, the membrane-bound immunoglobulins serve as receptors which, upon binding of a specific antigen, trigger the clonal expansion and differentiation of B lymphocytes into immunoglobulins-secreting plasma cells. Secreted immunoglobulins mediate the effector phase of humoral immunity, which results in the elimination of bound antigens. The antigen binding site is formed by the variable domain of one heavy chain, together with that of its associated light chain. Thus, each immunoglobulin has two antigen binding sites with remarkable affinity for a particular antigen. The variable domains are assembled by a process called V-(D)-J rearrangement and can then be subjected to somatic hypermutations which, after exposure to antigen and selection, allow affinity maturation for a particular antigen.
Synonyms: A3; IGKV2D28
Tractability: Antibody: its Gene Ontology location is reachable by antibodies, with high confidence; UniProt places it where antibodies can reach, with medium confidence; UniProt predicts a signal peptide or a membrane-spanning region.
Gene: Immunoglobulin variable (V) gene on chromosome 2 (89,959,979 to 89,960,748, forward strand). Ensembl gene ENSG00000242534.
Subcellular location: Secreted; Cell membrane
Pathways (Reactome):
Immune System: Antigen activates B Cell Receptor (BCR) leading to generation of second messengers; CD22 mediated BCR regulation; Classical antibody-mediated complement activation; FCERI mediated Ca+2 mobilization; FCERI mediated MAPK activation; FCERI mediated NF-kB activation; FCGR activation; Fc epsilon receptor (FCERI) signaling; Immunoregulatory interactions between a Lymphoid and a non-Lymphoid cell; Initial triggering of complement; Regulation of Complement cascade; Regulation of actin dynamics for phagocytic cup formation; Role of LAT2/NTAL/LAB on calcium mobilization; Role of phospholipids in phagocytosis
Disease: FCGR3A-mediated IL10 synthesis; FCGR3A-mediated phagocytosis; Potential therapeutics for SARS
Hemostasis: Cell surface interactions at the vascular wall
Vesicle-mediated transport: Scavenging of heme from plasma
Gene Ontology:
Molecular function: antigen binding
Biological process: immune response
Cellular component: blood microparticle; extracellular exosome; extracellular region; immunoglobulin complex; plasma membrane
Homologues: Orthologues: mouse Igkv2-109 (78% identical). Paralogues in human: IGKV2-28 (100% identical), IGKV2D-40 (88% identical), IGKV2D-29 (85% identical), IGKV2-24 (82% identical), IGKV2-30 (82% identical), IGKV2D-30 (81% identical), IGKV2D-24 (80% identical), IGKV2D-26 (79% identical), IGKV2-40 (75% identical), IGKV4-1 (62% identical), IGKV3-20 (61% identical), IGKV3-11 (60% identical), and 81 more.